PPT1 (palmitoyl-protein thioesterase 1)
Diseases named in the same sentence as PPT1 in open-access papers (continued):
Sharing a sentence is not in itself a finding about the gene and the disease.
nephritis (2 papers, 2024 to 2025). Inflammation of renal tissue. "As a result, PPT1 genetic deficiency or PPT1 inhibitors reduce autoantibody levels and attenuate nephritis in a transgenic SLE mouse model." (PMID 38169466, 2024). "Genetic deficiency in or chemical inhibition of PPT1 reduces anti-nuclear antibody levels and attenuates nephritis in B6.Sle1yaa mice." (PMID 38169466, 2024). "PPT1 genetic deficiency or chemical inhibition suppressed anti-DNA autoantibodies and attenuated nephritis in B6.Sle1yaa mice." (PMID 38169466, 2024). "Our data suggested that PPT1 modulated nephritis in B6.Sle1yaa mice." (PMID 38169466, 2024).
oral cancer (2 papers, 2025). "The genes PPT1 (palmitoyl-protein thioesterase 1), LILRA4 (leukocyte immunoglobulin-like receptor A4), and HCK (hemopoietic cell kinase) were correlated with a lower risk of oral cancer, while TNFRSF13C (tumor necrosis factor receptor superfamily member 13c) was linked to a higher risk." (PMID 40521000, 2025). "In addition, metabolic enzymes such as triosephosphate isomerase 1 (TPI1) and palmitoyl-protein thioesterase 1 (PPT1) have been shown to modulate ferroptosis sensitivity in OSCC cells, further underscoring the intimate link between ferroptosis and the metabolic adaptability of oral cancer." (PMID 41227330, 2025).
psychosis (2 papers, 2019 to 2023). "It established that the higher enzymatic PPT1 activity in FEP schizophrenia patients is associated with increased positive and negative syndrome scaling values, indicating more serious rates of developing psychosis." (PMID 36766729, 2023). "Similarly, a cohort study of approximately 36 individuals was performed to substantiate a bivariate correlation analysis of PPT1 enzymatic activity in first-episode psychosis (FEP) patients with a psychiatric assessment score." (PMID 36766729, 2023).
status epilepticus (2 papers, 2020 to 2022). Status epilepticus is defined as a continuous seizure lasting more than 30 min, or two or more seizures without full recovery of consciousness between any of them. "Because defects in the CLN1 gene (coding for palmitoyl-protein thioesterase 1 (PPT1)) are associated with CLN1 disease, the authors claim that PPT1 may have a protective role against excitotoxicity in in vivo-induced status epilepticus." (PMID 36012639, 2022). "However, a protective role of PPT1 from excitotoxicity was suggested in induced status epilepticus in rat." (PMID 33390903, 2020).
viral infection (2 papers, 2023 to 2024). "Mechanistically, we showed that PPT1 protected steady-state DCs from viral infection by promoting antigen degradation and endosomal acidification via V-ATPase recruitment." (PMID 38169466, 2024). "These include genes encoding for WDFY4, which is essential for cross-presentation of cell-associated antigens by cDC1 via the cytosolic pathway and PPT1, which protects XCR1+ cDCs from viral infection by promoting antigen degradation and endosomal acidification." (PMID 37954617, 2023).
behavioral disorders (1 paper, 2022). "In adults with nonspecific mental, motor, or behavioral disorders, in whom NCL is suspected, the first line of testing includes the just-mentioned enzymatic tests for PPT1, TTP1, CTSD, and CTSF, which, when normal, should prompt the clinician to perform ultrastructural testing." (PMID 35628533, 2022).
bladder cancer (1 paper, 2011). "More noteworthy is that PPT1 and hnRNP F could be new biomarkers for bladder cancer." (PMID 22363243, 2011). "Moreover, it suggests that PPT1 and hnRNP F could be new biomarkers for bladder cancer." (PMID 22363243, 2011).
bladder tumor (1 paper, 2011). "Nevertheless, based on the results of study, PPT1 is a potential biomarker for bladder tumor." (PMID 22363243, 2011).
colorectal cancer (1 paper, 2020). A primary or metastatic malignant neoplasm that affects the colon or rectum. "In one study, a close correlation between PPT1/CLN1 and TPP1/CLN2 expression was reported in the progression and metastasis associated with colorectal cancer." (PMID 32430003, 2020).
diabetic foot ulcers (1 paper, 2025). "Through investigation of the regulatory mechanisms driving excessive NLRP3-dependent inflammation in diabetic foot ulcers, the authors discovered that the thioesterase palmitoyl-protein thioesterase 1 (PPT1) regulates NLRP3 stability through de-acylation of NLRP3 at Cys-8." (PMID 39838868, 2025).
Kufs disease (1 paper, 2025). "Another pathological mechanism proposed for Kufs disease/CLN4 is an aberrant change in the palmitoylation of lysosomal and synaptic proteins caused by a decreased enzymatic activity of the depalmitoylating enzyme palmitoyl-protein thioesterase (PPT1/CLN1)." (PMID 40397740, 2025).
liver fibrosis (1 paper, 2025). "As for scarring, we identified the candidates Ppt1 and Cend1 that have demonstrated associations with kidney and liver fibrosis scarring, respectively." (PMID 41462614, 2025).
lung carcinoma (1 paper, 2022). "Furthermore, overexpression of S100A13 (P = 7.29e-4, t test), AZGP1 (P = 6.31e-4, t test), and PPT1 (P = 1.18e-4, t test), significantly increased the proliferation of lung cancer H1299 cells." (PMID 35027529, 2022).
lymphoma (1 paper, 2023). A malignant (clonal) proliferation of B- lymphocytes or T- lymphocytes which involves the lymph nodes, bone marrow and/or extranodal sites. "One mass that was observed in Ppt1+/+ un‐transplanted animals correlated with lymphoma and was considered to be related to a spontaneous tumor event that is reported to occasionally occur in wild‐type C57BL/6J animals after 300 days of age." (PMID 36876653, 2023).
Myocardial fibrosis (1 paper, 2025). "In conclusion, we demonstrated in vivo and in vitro that IPA alleviates aging‐related myocardial fibrosis through PPT1." (PMID 40539882, 2025). "This study investigates the role of indole‐3‐propionic acid (IPA) in aging‐related myocardial fibrosis and its regulatory effects on autophagy through palmitoyl‐protein thioesterase 1 (PPT1)." (PMID 40539882, 2025). "Using PPT1flox/flox Lyz2‐cre mice, it is demonstrated that macrophage‐specific deletion of PPT1 significantly reduced cardiac inflammation and myocardial fibrosis in aged mice." (PMID 40539882, 2025). "Additionally, we found that inhibiting PPT1 expression indirectly mitigates aging‐related myocardial fibrosis by modulating the autophagic function of macrophages." (PMID 40539882, 2025). "Furthermore, PPT1 silencing in macrophages reduced the expression of myocardial fibrosis markers in vitro." (PMID 40539882, 2025). "Supplementing IPA can alleviate the aging‐related myocardial fibrosis through PPT1." (PMID 40539882, 2025). "Next, we assessed whether IPA regulates myocardial fibrosis through its effects on PPT1 in the macrophages of aged rats." (PMID 40539882, 2025). "Mechanistically, IPA regulated PPT1 expression to modulate the PI3K‐AKT‐mTOR pathway, thereby restoring autophagic activity in senescent macrophages and suppressing both inflammation and aging‐related myocardial fibrosis." (PMID 40539882, 2025). "PPT1 is a key protein localized to lysosomes, and IPA can restore macrophage autophagy function by regulating PPT1 expresssions, thereby reducing aging‐related myocardial fibrosis and inflammation." (PMID 40539882, 2025).
retinal disease (1 paper, 2019). "Based on the association between PPT1 genetic variants and NCL in patients and animal models, how can we explain the non-syndromic nature of the retinal disease in Miniature Schnauzer dogs with the complex PPT1 exon 5 duplication variant?" (PMID 30541930, 2019).
tetanus (1 paper, 2019). A serious infectious disorder that follows wound contamination by the Gram-positive bacterium Clostridium tetani. "Ppt1 KO slices expressed a significantly lower magnitude LTP than WT [1.38 ± 0.004 (n = 7; P < 0.001, F value 201.16) compared with 1.71 ± 0.01 (n = 7), respectively, after second tetanus]." (PMID 30918483, 2019).
tumor (35 papers, 2008 to 2025). "Studies have shown that PPT1 is overexpressed in multiple malignant tumors and is strongly linked to tumor progression." (PMID 40416361, 2025). "We previously showed that PPT1-deficient mice had a lower tumor burden and a higher survival rate than PPT1-sufficient mice in xenograft tumor models, possibly due to 4-fold expansion of tissue-resident memory CD8+ T cells." (PMID 38169466, 2024). "Inhibition of PPT1 also enhanced anti-PD-1 antibody anti-tumor activity, associated with mediated secretion of IFN-β by macrophages, which is somewhat similar to our results analyzing immune cell infiltration." (PMID 37103469, 2023). "In vitro, HCQ, D661 (a more potent PPT1 inhibitor), or small interfering RNA against Ppt1 (siPpt1) were all able to convert M2 to M1 tumor-associated macrophages (TAMs)." (PMID 32780726, 2020). "In addition, the expression level of PPT1 was associated with the immune infiltration in the HCC tumor microenvironment, and PPT1 inhibitor DC661 significantly enhanced the anti-tumor immune response by promoting dendritic cell maturation and further promoting CD8+ T cell activation." (PMID 35277179, 2022). "Our findings show that PPT1 inhibition likely augments tumor immunity by at least 3 means: by causing an M2 to M1 macrophage polarization switch, by reducing the number of MDSCs in the tumor microenvironment, and by inducing IFN-β release from macrophages that stimulates T cell–mediated killing." (PMID 32780726, 2020). "The results revealed that PPT1 expression was significantly elevated in primary OS tumor tissues compared to normal tissues." (PMID 40416361, 2025). "Experimental validation revealed that elevated PPT1 expression is closely related to tumor cell proliferation, migration, invasion, and drug resistance in OS." (PMID 40416361, 2025). "GSVA and GSEA revealed up-regulation of functional and metabolic pathways in cells with high PPT1 expression, especially those related to drug resistance and tumor progression." (PMID 40416361, 2025). "Further analyses, including GO, KEGG, GSVA, and GSEA, shed light on the potential functions of PPT1 in OS, emphasizing its roles in drug resistance, tumor-promoting responses, and cellular signaling regulation." (PMID 40416361, 2025). "Immunofluorescence analysis demonstrated a significant increase in apoptosis within tumor tissues from the PPT1-knockdown group." (PMID 40416361, 2025). "For example, in oral squamous cell carcinoma, PPT1 promotes tumor cell proliferation, migration, and invasion, thereby enhancing tumor cell survival." (PMID 40416361, 2025). "In various tumor types, PPT1 exhibits consistent functions that are closely tied to tumor progression, immune evasion, and chemotherapy resistance." (PMID 40416361, 2025). "In vivo experiments further revealed that PPT1 expression levels in OS cells significantly affected tumor growth." (PMID 40416361, 2025). "Previous studies have demonstrated that PPT1 is increased in cancer and is crucial for constraining tumor growth." (PMID 38177255, 2024). "The potential utility of PPT1 blockade in conjunction with ICIs is being evaluated in an ongoing phase IIb study using GNS561/ezurpimtrostat, a novel inhibitor of PPT1, which has shown promising anti-tumor activity in pre-clinical models (NCT05448677)." (PMID 39267840, 2024). "In the context of HCC and its current therapies, preclinical data from murine melanoma models have shown that PPT1 inhibition enhances the anti-tumor activity of immune checkpoint inhibition using an anti-PD-1 antibody." (PMID 39267840, 2024). "In xenografts, PPT1 expression was associated with immune infiltration and the chloroquine derivative, presumably acting via PPT1, enhanced the anti‐tumor immune response by promoting dendritic cell maturation and T cell activation." (PMID 39429488, 2024). "As indicated by the results, ADCK3, HK3, and PPT1 were notably correlated with tumor purity, immune score, stromal score, and ESTIMATE score." (PMID 37434985, 2023).
tumor (continued). "Compared with peri-tumor controls, the expression of PPT1 was significantly increased in HCC tissues, which was consistent with the bioinformatics results obtained by the TCGA dataset." (PMID 37103469, 2023). "By performing quantitative proteomics and functional assays in vitro, the pathways affected by PPT1 inhibitors and the role and mechanisms by which they exert their anti-tumor effects were investigated." (PMID 37103469, 2023). "DC661 is a novel PPT1-targeted inhibitor that exerts an anti-lysosomal function and impairs tumor growth by inhibiting PPT1." (PMID 37103469, 2023). "In conclusion, this study identified three novel predictive biomarkers (ADCK3, HK3, and PPT1) correlated with tumor purity for HCC by bioinformatics methods." (PMID 37434985, 2023). "In the T-phase subgroup, PPT1 expression increased with increasing the tumor size and depth of infiltration." (PMID 37434985, 2023). "Antimalarial drugs or CNS drugs target the PPT1 and inhibit the de-palmitoylation of PPT1 enzyme to suppress the mTOR signaling pathway, thus reducing the accumulation of anti-tumor drugs in the lysosome." (PMID 37777749, 2023). "To investigate why PPT1 affects tumor progression, we analyzed the correlation between PPT1 expression and pathways, and the results showed that high expression of PPT1 in HCC promotes the cell cycle and epithelial–mesenchymal transition (EMT) pathway." (PMID 37103469, 2023). "Survival analyses for TCGA cancer patients also demonstrated that tumor expression of PPT1 was correlated with shorter overall survival in HCC." (PMID 37434985, 2023). "PPT1 can promote tumor growth and has already shown prognostic potential on its own in various cancer and HCC." (PMID 35783358, 2022). "Erianin efficiently decreased the tumor sizes, together with visibly reduced expression of PPT1 and phosphorylation of mTOR in the xenograft tumor tissues." (PMID 35004674, 2021). "Markedly, the expression of PPT1 and p-mTOR decreased in tumor cells derived from erianin-treated mice, as shown by the reduced brown staining." (PMID 35004674, 2021). "PPT1 has been reported to be overexpressed in cancer and is considered a valid target to control tumor growth." (PMID 35004674, 2021). "Taken together these results show that PPT1 inhibition changes macrophages from an M2 to an M1 polarization state and significantly reduces tumor MDSC infiltration in vivo." (PMID 32780726, 2020). "Taken together these data suggest that CQ derivatives that target PPT1 enhance the antitumor efficacy of anti–PD-1 Ab by targeting both the tumor cell and multiple immunosuppressive myeloid subsets." (PMID 32780726, 2020). "PP5/Ppt1 overexpression reduces pSer13-Cdc37 levels in a human tumor line and impairs activation of kinase clients, such as v-Src or C-Raf, in yeast and human cells." (PMID 18922470, 2008). "We show that Cdc37 and PP5/Ppt1 associate in Hsp90 complexes in yeast and in human tumor cells, and that PP5/Ppt1 regulates phosphorylation of Ser13-Cdc37 in vivo, directly affecting activation of protein kinase clients by Hsp90-Cdc37." (PMID 18922470, 2008). "Furthermore, hematoxylin and eosin (H&E) staining and terminal deoxynucleotidyl transferase dUTP nick end labeling (TUNEL) assays confirmed that PPT1 inhibits tumor cell apoptosis." (PMID 40416361, 2025). "Recent research indicates that protein depalmitoylation, mediated by depalmitoylating enzymes like PPT1, is crucial in regulating cell signaling, proliferation, and drug resistance by modulating protein stability and function, ultimately influencing tumor cell behavior." (PMID 40416361, 2025). "Notably, PPT1’s significant enrichment in the MAPK signaling pathway highlights its aberrant activation and close association with tumor cell proliferation and survival." (PMID 40416361, 2025). "Specifically, PPT1 may enhance drug resistance, as well as tumor proliferation and invasion, in OS cells via depalmitoylation." (PMID 40416361, 2025).
tumor (continued). "Furthermore, genetic inhibition of S-depalmitoylase PPT1 suppresses tumor growth, and high PPT1 expression tends to aggravate the survival of patients with numerous distinct cancers." (PMID 38177255, 2024). "The results showed that PPT1 was more highly expressed in higher malignant tumors, expression was positively correlated with tumor metastasis, and PPT1 may play a role in promoting the progression of HCC." (PMID 37103469, 2023). "Data LIHC_GSE76297 was used to confirm the high expression of PPT1 in HCC tumor tissues." (PMID 37006288, 2023). "Recently, it has been reported that PPT1 is essential for the function of lysosomes, which, as the center of cellular energy sensing and metabolic regulation, play a driving role in the malignant progression of tumor cells." (PMID 37006288, 2023). "The PPT1 inhibitor DC661 has notably improved the anti-tumor immune response." (PMID 38067206, 2023). "In addition, the expression level of PPT1 was associated with the immune infiltration in the HCC tumor microenvironment and PPT1 inhibitor DC661 significantly enhanced the anti-tumor immune response." (PMID 35277179, 2022). "The PPT1 was identified by photoaffinity pulldown as a target of a chloroquine derivative preventing lysosomes acidification and reducing melanoma cells viability and tumor growth in vivo, and was subsequently involved in HCC resistance to the kinase inhibitor sorafenib." (PMID 39429488, 2024). "Therefore, we decided to find out whether PPT1 depends on PKM2 to promote tumor progression through autophagy." (PMID 37006288, 2023). "We demonstrated that SPRY4 undergoes a dynamic palmitoylation cycle regulated by ZDHHC7 and PPT1, which modulates MAPK signaling and subsequently affects tumor cell proliferation, migration, apoptosis, and drug resistance." (PMID 40416361, 2025). "By specifically targeting PPT1, GNS561 disrupts the autophagy pathway in tumor cells, leading to lysosomal membrane permeabilization." (PMID 40416361, 2025). "Our findings demonstrate that PPT1 activates the MAPK signaling pathway through depalmitoylation, thereby enhancing tumor cell proliferation and invasion while contributing to cisplatin resistance." (PMID 40416361, 2025). "Compared with the control group, the injection of Huh-7 cells stably overexpressing PPT1 and PKM2 significantly promoted tumor growth, while after treatment with chloroquine, tumor growth was inhibited to some extent." (PMID 37006288, 2023). "PPT1 and HK3 were overexpressed in tumor and its high expression was correlated with poor prognosis, while high ADCK3 expression was correlated with better survival." (PMID 37434985, 2023). "High HK3 and PPT1 expression and low ADCK3 expression resulted in high tumor purity, high immune score, high immune score, high stromal score, and high ESTIMATE score." (PMID 37434985, 2023). "In both datasets, HCC tissues had lower HK3 expression and higher PPT1 and ADCK3 expressions than paired adjacent non-tumor tissues." (PMID 37434985, 2023). "PPT1, as a lysosomal-related gene with prognostic value, was experimentally analyzed for its expression in HCC patients and its effects on tumor cell proliferation were investigated." (PMID 37103469, 2023). "For intervention, HCQ, an inhibitor of PPT1, was applied to augment the level of AEG-1 palmitoylation, which retards the tumor growth of HCC in xenograft model." (PMID 36276642, 2022). "Furthermore, high HK3 and PPT1 expressions and low ADCK3 expression resulted in high tumor purity, high immune score, high stromal score, and high ESTIMATE score." (PMID 37434985, 2023). "In addition, IHC staining showed that Ki-67 levels were notably increased in the tissues of mice treated with stable overexpression of PPT1 and PKM2, suggesting that tumor proliferation was obvious." (PMID 37006288, 2023).